RNU7-90P (RNA, U7 small nuclear 90 pseudogene)
Gene: Small nuclear RNA gene on chromosome 16 (72,673,503 to 72,673,564, forward strand). Ensembl gene ENSG00000238731.
Homologues: Orthologues: chimpanzee U7 (98% identical). Paralogues in human: U7 (82% identical), RNU7-80P (81% identical), RNU7-129P (79% identical), RNU7-48P (79% identical), RNU7-57P (79% identical), RNU7-60P (79% identical), RNU7-140P (77% identical), RNU7-65P (77% identical), RNU7-79P (77% identical), RNU7-84P (77% identical), RNU7-154P (76% identical), RNU7-170P (76% identical), and 142 more.